CD4 (CD4 molecule)
Diseases named in the same sentence as CD4 in open-access papers (continued):
Sharing a sentence is not in itself a finding about the gene and the disease.
infection (continued). "In conclusion, our findings here demonstrate that both CD4 and CD8 T cells play a role in acute pathogenesis during ML29 infection in STAT1-/- mice; 100% survival is only achieved with a double CD4 and CD8 T cell depletion." (PMID 36289695, 2022). "Consistent with the findings from ILN, these results indicated that VLPs containing both AMA1 and MIC induced CD4+ T cell responses, and lessened the production of inflammatory cytokines IFN-γ and TNF-α in the spleen upon P. berghei challenge infection." (PMID 35468726, 2022). "Blood CD4+ T and CD8+ T cell responses in mice immunized with VLPs before and after the challenge infections were determined by FACS analysis." (PMID 35468726, 2022). "We showed that pre-depleting NK cells significantly impaired type 1 T cell responses to the infection, but contrarily enhanced FOXP3+ Treg cells and IL-10-producing CD4 T cells, leading to enhanced disease severity and chlamydial growth in the lung." (PMID 35185930, 2022). "An enhanced ability to enter low-density CD4 cells (CD4/low+CCR5/high) is indicative of an M-tropic entry phenotype, whereas poor infection of cells with a low density of CD4 is indicative of a T cell-tropic entry phenotype." (PMID 35975998, 2022). "Infections established by viruses with lower VRC induce less proinflammatory cytokines during acute infection in adults and lower CD4+ and CD8+ T-cell immune activation and exhaustion." (PMID 35634290, 2022). "One of the definite roles of CD4+ T cells in anti-TB immunity is to evolve into Th1 effector cells and produce IFN-γ and TNF-α to directly activate macrophages to control infection or kill MTB-infected macrophages." (PMID 36363564, 2022). "In response to Chlamydia muridarum infection, a pathogen-specific subset of CD4+ TRM cells is formed at the interface of the FRT epithelia and lamina propria, which mediates protection from secondary infection." (PMID 35488095, 2022). "Then the proportion of CD4+ T cells and CD8+ T cells began to decrease on day 6, probably due to the depletion of cells during the clearance phase of infection." (PMID 35814662, 2022). "Taken together, these results indicate that LmCen-/- immunization induces CD4+ TRM cells with a cytotoxic response after challenge, and such response is equivalent to healed infection." (PMID 35419001, 2022). "Similar observations were made using an orthogonal approach by transducing CD4+ T cells from SMARTA mice with shCacnb1 (Amt+) and shCtrl (GFP+) followed by transfer of T cells at a 1:1 ratio and infection with LCMVARM." (PMID 35440113, 2022). "In the recent infection group, 81.2%, 87.5% and 68.7% of the individuals responded to Pep-S, Pep-M and Pep-N, respectively, in terms of the frequency of TNF-α-producing CD4+ T-cells." (PMID 34967260, 2022). "It has been reported that SARS-CoV-2-specific CD4+ and CD8+ T cells are capable of activating and proliferating ex vivo for at least 10 months after infection." (PMID 36499448, 2022). "For adaptive T cell responses, both CD4 and CD8 T cells participate in protection from infections and disease." (PMID 35185930, 2022). "Our data supports that a heterologous booster with Corbevax enhances naïve CD4/CD8 T lymphocytes and CD8 T lymphocyte effector memory responses, inducing stronger effector immune memory for a longer duration, protecting against infection." (PMID 36560556, 2022). "Regarding the adaptive immune response, it has been reported that CD4+ and CD8+ T-cell responses appear early after infection or vaccination, cross-recognize viral variants, are over time stable and persist in vulnerable populations, albeit with a low amount." (PMID 35967321, 2022). "Specifically, we isolated CD4+ T cells from HIV-1 uninfected, deidentified donor PBMCs and activated them with phytohemagglutinin (PHA) and IL-2 for 3 days before infection via spinoculation with HIV ADA." (PMID 36125890, 2022).
infection (continued). "The numbers of total CD4+ and CD8+ T cells at day 4 post re-infection were comparable to numbers recorded at the peak of the primary infection (day 7–8) in this model." (PMID 35108347, 2022). "After 20 hours of infection, equivalent to 1 replication cycle, we performed FLIPS and quantified the proportion of full-length sequences present in each CD4+ T cell subset." (PMID 35133986, 2022). "The infection is achieved through direct C-T-C contact between HTLV-I-infected CD4+ T cells and healthy CD4+ T cells." (PMID 36016341, 2022). "The CD4+ T cell response is induced early during SARS-CoV-2 infection, but the CD8+ T cell response takes more time to build up post-infection." (PMID 36447262, 2022). "SARS-CoV-2-specific CD4+ and CD8+ TRM cells were present in the lungs up to 10 months post infection, and the transcriptome of these cells differed from peripheral blood T cells." (PMID 36211412, 2022). "In the future, it would be valuable to characterize the dynamic development of CD4/CD8 effector and memory CTL elicited by PRRSV MLV vaccines, and the efficacy to protect homologous and heterologous infections." (PMID 36798517, 2022). "As expected, TNT inhibitors significantly decreased infection of HIV-C-loaded-DCs as well as HIV- and HIV-C-infected-DC/CD4+ T-cell co-cultures." (PMID 35204813, 2022). "During primary infection, neutrophils were able to boost IL-2 and IFN-γ production by CD4+ and CD8+ T cells and IL-17A production by CD4+ T cells." (PMID 35185880, 2022). "Due to the long coding region of PRDM1, the infection efficiency in primary T cells is very low, it is difficult to acquire a sufficient number of PRDM1-overexpression CD4+ or CD8+ T cells for further multiomics sequencing." (PMID 35572579, 2022). "Here, we show for the first time that neutrophils can differentially modulate CD4+ and CD8+ T-cell functions in primary infection in the macaque model." (PMID 35185880, 2022). "Some of those reveal that CD4+ and CD8+ memory T cell responses were identified in the blood of 70-100% of SARS-CoV patients four and six years after infection and even detected CD8+ T cell responses 11 years post-infection." (PMID 35833134, 2022). "Activation of immune cells, especially CD4+ T cells, is essential for HIV-1 replication and the establishment of infection." (PMID 35336878, 2022). "During infection, all RSV-specific CD4+ T cells displayed upregulated CCR5 and downregulated CD62L in both blood and BALs." (PMID 36211412, 2022). "Lastly, as the expression of activation markers (CD38, HLA-DR, Ki-67 or PD-1) on antigen-specific T-cells is indicative of active infection, we defined the expression of these markers on SARS-CoV-2-responding CD4 T-cells." (PMID 34140294, 2022). "(B–C) The sorted uninfected CD4+ Tm cells in panel A, along with total CD4+ Tm cells, were exposed to F4.HSA and assessed by flow cytometry for infection rates 3 days later." (PMID 35787792, 2022). "Infected Bcl3flx/flxZbtb46 cre mice failed to clear the parasite in brain, spleen and lung and had impaired Th1 immune responses, with reduced production of IFN-γ from antigen-specific CD4+ and CD8+ T cells in the adaptive phase of the infection." (PMID 36318581, 2022). "A higher level of CD4+ T cells was found in VLP-immunized mice before and after challenge infection compared to naïve control (*p < 0.05)." (PMID 35468726, 2022). "Children showed a dominant antibody and plasmablast response and a lower frequency of specific memory B and CD4+ and CD8+ T cells with reduced secretion of proinflammatory cytokines 4 months after infection." (PMID 36437276, 2022). "Overall, these specific T CD4+ and CD8+ cells, induced by a previous infection or vaccination provide a broad immune coverage against the Omicron variant as well." (PMID 36362500, 2022). "Follicular helper CD4+ T cells (TFH) are highly permissive to HIV and major foci of virus expression in both untreated and treated infection." (PMID 36420277, 2022).
infection (continued). "After infection, IFN-γ, mainly produced by NK cells and CD4+ T cells, stimulates macrophage activation, inducing high level of Th1 proinflammatory cytokines (e.g., IL-12, IL-2, IL-18, IL-27) and low levels of anti-inflammatory molecules." (PMID 36060742, 2022). "The frequencies of CD4, CD8 and DN T cells in lungs from Hif1a cKO and WT mice before or after infection with M. tuberculosis were instead similar." (PMID 36064840, 2022). "CD4 CM cells showed increased pyroptosis in blood on day 14 (P = 0.035), and in GALT and lymphoid tissues on day 10 following infection (for colon, P = 0.003; for mesenteric LNs, P = 0.004; for spleen, P = 0.005; for pelvic LNs, P = 0.008)." (PMID 36000842, 2022). "In agreement with results above, CD4+ bTRM and CD8+ bTRM numbers were increased after infection with Lm ΔactA." (PMID 35614490, 2022). "The analysis of lymphocyte subsets in the circulation of animals experimentally infected with M. bovis showed the sequential role of the γδ, CD4+, and CD8+ T cells during infection." (PMID 35689185, 2022). "After hirame novirhabdovirus (HIRRV) infection or immunization, the ratios of CD8+ T cells increased more rapidly than CD4+ T cells, which indicates that CD8+ T cells play main roles in the response to HIRRV." (PMID 37073166, 2022). "These sorted populations (along with total CD4+ Tm cells as a comparison control) were then exposed to HIV-F4.HSA for 3 days and then assessed by FACS for infection rates." (PMID 35787792, 2022). "Failure of innate immune cells to eradicate Mtb bacilli results in activation and recruitment of adaptive CD4+ Th1 and cytotoxic CD8+ T cells that typically surround Mtb-infected macrophages at the site of infection forming the granuloma." (PMID 36591229, 2022). "Infection with HCMV upregulates MHC class II expression on the RPE cells, and this allows for sufficiently robust antigen presentation to initiate CD4 T cell control of the infection." (PMID 36445084, 2022). "In a similar manner, reconstitution of Rag1-/- mice with CD4 T cells that overexpress IFN-γ induces pulmonary pathology and exacerbates bacterial burden in the lung while controlling infection outside of the lungs." (PMID 35877763, 2022). "To assess the function of these NK cells, we isolated allogeneic CD4+ T cells from the PBMCs of healthy donors and performed CD3 and CD28 co-stimulation for three days prior to infection with 800 ng of p24 of X4-tropic NL4-3 or R5-tropic NFNSX for 24 h." (PMID 35013215, 2022). "Tnfsf8 expression is mostly dispensable for control of infection outside of the lungs, and the overabundance of IFN-γ-producing CD4 T cells observed in the lungs of Tnfsf8-/- mice following infection has been shown to drive immunopathology." (PMID 35877763, 2022). "Several weeks upon infection, C57BL/6 mice develop a strong type 1 helper (Th1) CD4+ T cell response." (PMID 36034693, 2022). "The authors showed that in people resistant to infection, the expression of DPP-4 in CD4+ T cells was significantly increased compared to HIV-negative and unexposed people (p = 0.0003)." (PMID 35330038, 2022). "IPEC-J2 were treated with NF-κB inhibitor (PG490) for 12 h prior to infection with PCV2 and co-cultured with CD4+ T cells." (PMID 36366564, 2022). "In contrast, following infection with JKD6159-gD, activated CD4+ T cells were predominantly IL-17 producing Th17, and of the divided cells, 40% downregulated CD62L, 26% upregulated CCR6, while only 20% upregulated CXCR3." (PMID 35637249, 2022). "This functional feedback of NKT cells on DCs, especially the preferential promoting effect on CD8α+ and CD103+ DC subsets in lymphoid and non-lymphoid tissues, significantly impacts the systemic and local adaptive CD4 and CD8 T cell responses in infections." (PMID 35185930, 2022). "The pure human CD4+ and CD8+ T cells were incubated with H1N1 (A/California/07/2009) at a MOI (multiplicity of infection) of 10 for 1h in vitro respectively." (PMID 35317717, 2022).
infection (continued). "Th17 cell expression of mucosal migration receptors (CCR6 and α4β7), as well as HIV co-receptors (CD4, α4β7, CCR5, and CXCR4), participates in the remarkable capacity of these cells to disseminate HIV following initial infection." (PMID 35197986, 2022). "We show that, when testing history is combined with knowledge of recent infection using RITA, the current public health definition of late diagnosis (CD4 <350 cells/mm3) increasingly overestimates rates of late presentation." (PMID 36069144, 2022). "Acute and memory CD4+ T cell reactivity to structural SARS-CoV-2 proteins increase with age, whereas CD8+ T cell responses increase with time post-infection." (PMID 36499448, 2022). "To assess the functional polarization of hepatic CD4- and CD4+ iNKT cells in more detail we analyzed T-bet and GATA-3 expression in the steady state and during acute and secondary infection." (PMID 36159876, 2022). "While the infection of total PBMCs led to the activation of the different cell subsets, as evidenced before, the proportion of CD69-expressing CD4+ and CD8+ T cells, B cells, or NK cells among lymphocytes was not increased when monocytes were depleted." (PMID 35615366, 2022). "In a separate study, HIV-1 infected CD4+ T cells were found to have decreased levels of glycolytic enzymes PGK and PGI three days post-infection, indicating shunting of glucose through the PPP rather than glycolysis." (PMID 36467738, 2022). "Early retrospective studies indicated that SRAR and MERS patients had a significant reduction of T cells counts including CD4+ and CD8+ cells during the acute infection phase." (PMID 36290585, 2022). "These analyses have indicated that the CD4 T cells elicited by IBV infection are quite diverse, and at the peak of infection, IBV-specific CD4 T cells are distributed widely across the secondary lymphoid tissues in the periphery." (PMID 35215193, 2022). "Specific CD4+ and CD8+ T cell responses were detectable in both children and adults 4 and 12 months after infection, albeit at a lower frequency in children." (PMID 36437276, 2022). "5-day-old Pekin ducklings were infected with the R38K, T151A, and R304M mutant viruses and the rY and rPS control viruses, and the levels of IL-2, IL-17, IFN-γ, TNF-β, CD4, and CD8 mRNAs in brain and thymus were measured at 7 days after infection." (PMID 36016955, 2022). "A wide range of protein epitopes compete for binding to MHC class I and II molecules during an infection, leading to CD8+ and CD4+ T cell activation, respectively." (PMID 36146606, 2022). "The function of CD4 T cells during the initial priming phase of infection limits exhaustion of CD8 T cells, which can rapidly recall the viral memory in future infection." (PMID 35967412, 2022). "Mycobacterium tuberculosis is a typical intracellular pathogen, and T cell-mediated immune responses, comprising CD4+ T cells, CD8+ T cells, or both T cell subsets, are crucial for controlling the infection and postponing the onset of the disease." (PMID 36569899, 2022). "Studies on lung CD4+ and CD8+ TRM cells post-infection provide an insight to the role of these cells in defence against respiratory pathogens." (PMID 36211412, 2022). "The presence of SARS-CoV-2 CD4+ and CD8+ T-cell responses up to 6 months after infection in mild to moderate clinical course and persistent immunological alterations in the memory compartment have been described after SARS-CoV-2 infection." (PMID 35619701, 2022). "By both measures to quantify CD4 T cells, IBV-specific cells are seen to be distributed across the animal at a peak time (day 11) after infection and include both the site of infection and the peripheral lymphoid tissues." (PMID 35215193, 2022). "Nonetheless, DCs express both CD4 and CCR5 HIV-1 co-receptors where DC-mediated cell-free HIV-1 trans-infection of T cells is well documented." (PMID 35215997, 2022). "Conversely, intrahepatic CD4+ and CD8+ effector T lymphocytes increased more than 5-fold after infection." (PMID 35720410, 2022).
infection (continued). "In particular, Th1 CD4+ T-cells are specific for HPV-16 E6, E7, and E2, because they are found in the peripheral blood of immunocompetent individuals with HPV confirmed infection." (PMID 35888579, 2022). "CD4+ T cells are crucial in the whole-body resistance to HAV infection, and they produce a large number of cytokines in the early stages of infection, including IFN-γ, TNF-α, IL-2, and IL-21." (PMID 36248427, 2022). "During cis-infection, HIV-1 binds to the CD4 receptor and coreceptor on a DC, as in macrophages and CD4 T cells." (PMID 36146843, 2022). "The polyfunctional CD4 T cells producing multiple proinflammatory cytokines (IFN-γ, TNF-α, and IL-2) which one correlate with protection from infection and disease." (PMID 35638072, 2022). "After 10 months post-infection, we observed a sustained SARS-CoV-2-specific CD4+ T-cell response directed against M-protein, but responses against S- or N-proteins were lost over time." (PMID 34967260, 2022). "In humans, a leukocytic infiltrate occurs in the endocervix in response to HSV, and CD4 and CD8 T cells infiltrate the dermis during and after infection." (PMID 35432373, 2022). "Overall, while the timing of cART positively impacts CD4+ T cell response restoration, HIV suppression results in better control of CD8+ T cell responses in the primary infection site as well as in extrapulmonary organs." (PMID 34855621, 2022). "After activation in the lymph nodes, CD4+ and CD8+ T-cells change the expression of homing receptors and migrate via several mechanisms to the site of infection." (PMID 36052083, 2022). "CD4+ T cells are necessary to generate a CD8+ CTL response, and both T lymphocytes play an important role in viral clearance responses after infection with herpesviruses." (PMID 36016245, 2022). "As HIV infects and replicates preferentially in activated CD4+ T cells, the ability of HIV-susceptible CD4+ cells at the portals of entry to remain quiescent despite HIV exposure may preclude HIV replication in these cells and reduce the risk of establishing a productive infection." (PMID 35746615, 2022). "As in the lungs, significant induction of IFN-γ by CD4+ and CD8+ T lymphocytes was noted in the spleens of mice during secondary infection with B. abortus or B. melitensis." (PMID 36032120, 2022). "While the innate immune responses help temporize infection, adaptive immune responses, in particular CMV specific CD4+ and CD8+ T-cells, are critical in control of CMV infection." (PMID 36366468, 2022). "After infection with SARS-CoV-2, virus-specific CD8+ and CD4+ T cells can be studied by tetramer staining in peripheral blood." (PMID 36437276, 2022). "Vaccinated macaques showed SIV-specific CD4+ T cells, as well as IFNγ-producing CD8+ T cells, in the early phases of infection." (PMID 36033843, 2022). "Previous studies have also suggested that CD4+ T cells and IFN-γ are required to establish protective immunity against infection with Babesia parasites." (PMID 35812841, 2022). "Within T cells, the memory response is skewed toward more CD4+ T cell responses than that of CD8+ T cells, despite their similar levels immediately after infection." (PMID 36119105, 2022). "Vhl cKO mice showed low levels of CD4 T cells in spleens and mediastinal lymph nodes (MLN) at 8 weeks after infection." (PMID 36064840, 2022). "Numerous proinflammatory mediators are produced during infection, including IFN-α, IL-4, IL-10 and IFN-γ, with a high circulation of CD8+ and CD4+ lymphocytes, monocytes and leukocytes." (PMID 36298749, 2022). "First, we monitored total infection with R5/X4 HIV-GKO (csGFP+/mKO2+, csGFP+/mKO2−, and mKO2+/csGFP−) over 7 days, in primary CD4+ T cells stimulated with IL-2 or IL-15 at equimolar concentration." (PMID 35499323, 2022). "The infection of HIV results in a gradual change in the number of CD4-expressing T cells, which can be measured by CD4 count." (PMID 35205215, 2022).